DMPK (DM1 protein kinase)
Description:
Non-receptor serine/threonine protein kinase which is necessary for the maintenance of skeletal muscle structure and function. May play a role in myocyte differentiation and survival by regulating the integrity of the nuclear envelope and the expression of muscle-specific genes. May also phosphorylate PPP1R12A and inhibit the myosin phosphatase activity to regulate myosin phosphorylation. Also critical to the modulation of cardiac contractility and to the maintenance of proper cardiac conduction activity probably through the regulation of cellular calcium homeostasis. Phosphorylates PLN, a regulator of calcium pumps and may regulate sarcoplasmic reticulum calcium uptake in myocytes. May also phosphorylate FXYD1/PLM which is able to induce chloride currents. May also play a role in synaptic plasticity.
Synonyms: MT-PK; DMK; DM1PK; MDPK; DM; DM1
Tractability: Small molecule: a high-quality ligand is known; it has a binding pocket of medium quality; it belongs to a druggable protein family. Antibody: UniProt places it where antibodies can reach, with medium confidence; UniProt predicts a signal peptide or a membrane-spanning region; its Gene Ontology location is reachable by antibodies, with medium confidence. PROTAC: ubiquitination databases record sites on it; a small molecule that binds it is known.
Target class: Kinase; Protein Kinase; AGC protein kinase DMPK family; AGC protein kinase GEK subfamily; AGC protein kinase group; Enzyme
Safety:
Unwanted effects reported when the protein is acted on. In parentheses: how it was acted on, where the effect was seen, and who reports it.
heart disease (cardiovascular system; source: Force et al. (2011))
Gene: Protein-coding gene on chromosome 19 (45,769,709 to 45,782,552, reverse strand). Ensembl gene ENSG00000104936.
Subcellular location: Endoplasmic reticulum membrane; Nucleus outer membrane; Mitochondrion outer membrane; Sarcoplasmic reticulum membrane; Cell membrane; Cytoplasm, cytosol; Mitochondrion membrane (Isoform 1); Mitochondrion membrane (Isoform 3)
Subcellular location (Human Protein Atlas): Cytosol; Vesicles
Pathways (Reactome):
Muscle contraction: Ion homeostasis
Gene Ontology:
Molecular function: ATP binding; myosin phosphatase regulator activity; protein binding; protein serine/threonine kinase activity; protein kinase activity; protein serine kinase activity
Biological process: muscle cell apoptotic process; nuclear envelope organization; protein phosphorylation; regulation of heart contraction; intracellular calcium ion homeostasis; regulation of myotube differentiation; regulation of skeletal muscle contraction by calcium ion signaling
Cellular component: mitochondrial outer membrane; cytosol; endoplasmic reticulum membrane; nuclear membrane; plasma membrane; sarcoplasmic reticulum membrane; mitochondrial membrane; nuclear outer membrane
Genetic constraint (gnomAD): Loss-of-function variants: 31 observed, 62.49 expected, observed/expected ratio (o/e) 0.5, 90% interval 0.37 to 0.67. The synonymous counts are far from expectation, so gnomAD's model fits this gene poorly and the ratio says little. Missense variants: 890 observed, 845.51 expected, observed/expected ratio (o/e) 1.05, 90% interval 1 to 1.11. Synonymous variants: 464 observed, 371.71 expected, observed/expected ratio (o/e) 1.25, 90% interval 1.16 to 1.35.
Homologues: Orthologues: chimpanzee DMPK (93% identical), pig DMPK (89% identical), guinea pig DMPK (88% identical), mouse Dmpk (86% identical), dog DMPK (82% identical), rat Dmpk (78% identical), Drosophila melanogaster dop (25% identical), Caenorhabditis elegans kin-4 (23% identical), Caenorhabditis elegans wts-1 (22% identical), Drosophila melanogaster CG32944 (15% identical), Caenorhabditis elegans M03C11.1 (14% identical), Caenorhabditis elegans T24D5.4 (3% identical). Paralogues in human: MAST2 (30% identical), MAST4 (30% identical), MAST1 (29% identical), MAST3 (27% identical), LATS2 (26% identical), LATS1 (26% identical), SGK1 (19% identical), SGK3 (19% identical), SGK2 (18% identical), MASTL (17% identical), STK32C (16% identical), STK32B (15% identical), and 1 more.
Diseases named in the same sentence as DMPK in open-access papers:
DMPK is named in the same sentence as 98 diseases in open-access papers, as found by Europe PMC text mining. Sharing a sentence is not in itself a finding about the gene and the disease. The quoted sentences say what the papers report.
myotonic dystrophy type 1 (251 papers, 2008 to 2026). Steinert disease, also known as myotonic dystrophy type 1, is a muscle disease characterized by myotonia and by multiorgan damage that combines various degrees of muscle weakness, arrhythmia and/or cardiac conduction disorders, cataract, endocrine damage, sleep disorders and baldness. "Myotonic dystrophy type 1 (DM1) is caused by a (CTG)n expansion in the DMPK gene, leading to a multisystemic manifestation and broad disease presentation." (PMID 40606545, 2025). "Myotonic Dystrophy type 1 (DM1) is an autosomal dominant disorder caused by a CTG repeat expansion in DMPK." (PMID 40558510, 2025). "There was high concordance with repeat size estimates from conventional PCR-based methods although larger repeats such as FMR1 associated with fragile X syndrome and DMPK repeat expansion associated with myotonic dystrophy type 1 were underestimated." (PMID 39349043, 2025). "Myotonic dystrophy type 1 (DM1) is a progressive multisystemic disease caused by a CTG repeat expansion in the DMPK gene." (PMID 41226829, 2025). "Conversely, while most intronic repeats were not genotyped, we found a high genotyping rate in the intronic locus that causes spinocerebellar ataxia 36 (NOP56, 30.1–98.3%) and in the one that causes myotonic dystrophy type 1 (DMPK, myotonic dystrophy type 1)." (PMID 40004498, 2025). "The DMPK-CTGexp mutation causes myotonic dystrophy type 1 (DM1), a neuromuscular disease with onset times that span from in utero to late adulthood and highly variable symptom severity." (PMID 40259070, 2025). "Myotonic dystrophy type 1 (DM1) is caused by expanded CTG repeats in the DMPK gene, causing the accumulation of toxic RNA that sequesters RNA‐binding proteins." (PMID 41241935, 2025). "Background/Objectives: Missplicing caused by toxic DMPK-mRNA is described as a hallmark of myotonic dystrophy type 1 (DM1)." (PMID 40149583, 2025). "Myotonic dystrophy type 1 (DM1) is a highly variable multi-systemic disorder caused by an expansion of a CTG trinucleotide repeat in the noncoding region of the DMPK gene." (PMID 41441388, 2025). "Myotonic dystrophy type 1 (DM1) is a slowly progressive disease caused by abnormal CTG repetitions on the dystrophia myotonica protein kinase (DMPK) gene." (PMID 39031377, 2024). "Myotonic dystrophy type 1 (DM1) is the most common muscular dystrophies in adults caused by a CTG-trinucleotide expansion in the 3 ́ untranslated region (UTR) of the dystrophia myotonica protein kinase (DMPK) gene." (PMID 38972019, 2024). "Myotonic Dystrophy Type 1 (DM1) is a genetic disorder caused by an expanded CTG repeat in the DMPK gene, leading to nuclear RNA foci and reduced MBNL1 levels." (PMID 39595972, 2024). "Genetic examinations of LECs in dystrophia myotonica patients have revealed the presence of the dystrophia myotonica-protein kinase (DMPK) gene mutation in these cells." (PMID 38439904, 2024). "Myotonic dystrophy type 1 (DM1) is caused by an expanded CTG repeat in the 3’ untranslated region (UTR) of the dystrophia myotonica-protein kinase (DMPK) gene." (PMID 39501809, 2024). "Myotonic Dystrophy type 1 (DM1) is a dominantly inherited neuromuscular disorder caused by the expansion of CTG repeats in the DMPK gene leading to abnormal RNA processing and alteration of various protein functions." (PMID 36935893, 2023). "CTG repeat expansion in the 3′ UTR of the myotonic dystrophy protein kinase (DMPK) gene has been linked to myotonic dystrophy type 1, a neuromuscular disease that can cause cardiac conduction disorders and cardiomyopathy." (PMID 37283586, 2023). "Direct variant analysis of WGA-DNA from EVTs clearly detected the expanded maternally inherited DMPK allele, indicating that the coming child would develop myotonic dystrophy type 1." (PMID 37829280, 2023). "Myotonic dystrophy type 1 (DM1) is an incurable multisystem disease caused by a CTG-repeat expansion in the DM1 protein kinase (DMPK) gene." (PMID 36352383, 2022).
myotonic dystrophy type 1 (continued). "Myotonic dystrophy type 1 (DM1) is a multisystemic disease caused by an expansion of the CTG repeat sequences in the 3′UTR of the DMPK gene." (PMID 36060259, 2022). "By contrast, myotonic dystrophy type 1 (DM1) is caused by CTG nucleotide repeat expansion in the myotonic dystrophy protein kinase (DMPK) gene." (PMID 36147041, 2022). "Myotonic dystrophy type 1 (DM1) is a multisystemic neuromuscular disorder caused by the expansion of a CTG repeat in the 3′-UTR of DMPK, which is transcribed to a toxic gain-of-function RNA that affects splicing of a range of genes." (PMID 35741732, 2022). "DMPK is notable for causing myotonic dystrophy type 1 due to a repeat expansion within an intronic region in carriers that leads to altered gene expression of genes within that region." (PMID 34294691, 2021). "Myotonic dystrophy type 1 (DM1) is a neuromuscular disorder caused by a non-coding CTG repeat expansion in the DMPK gene." (PMID 34025359, 2021). "Myotonic dystrophy type 1 (DM1) is an autosomal dominant multisystemic disorder caused by unstable CTG-repeat expansions in the DMPK gene." (PMID 34262431, 2021). "Myotonic dystrophy type 1 (DM1) is a dominantly inherited neuromuscular disease caused by expansion of a CTG trinucleotide repeat in the 3′ untranslated region of DMPK." (PMID 33503262, 2021). "Myotonic dystrophy type 1 (DM1) is caused by CTG-repeat expansions in the 3′ UTR of the DMPK gene, which are inherited autosomal dominant." (PMID 34262431, 2021). "The cause of myotonic dystrophy type 1, known as Steinert disease, are alterations to DMPK, while myotonic dystrophy type 2 results from defects in CNBP (also known as ZNF9)." (PMID 32580419, 2020). "Myotonic dystrophy type 1 (DM1) is caused by a CTG (Cytosine-Thymine-Guanine) expansion in the 3′ untranslated region of the dystrophia myotonica-protein kinase (DMPK) gene." (PMID 33171734, 2020). "Myotonic dystrophy type 1 (DM1) is a neuromuscular disease caused by expanded CTG repeats in the myotonic dystrophy protein kinase (DMPK) gene." (PMID 32683410, 2020). "Myotonic dystrophy type 1 (DM1) is a multi-system disorder caused by CTG repeats in the myotonic dystrophy protein kinase (DMPK) gene." (PMID 32407311, 2020). "Myotonic dystrophy type 1 is caused by a trinucleotide cytosine-thymine-guanine (CTG) repeat expansion in the dystrophia myotonica protein kinase (DMPK) gene." (PMID 33033872, 2020). "Myotonic dystrophy type 1 (DM1) is a neuromuscular diseases caused by inherited CTG repeat expansion in the gene encoding DM Protein Kinase (DMPK)." (PMID 31127296, 2019). "The congenital form of myotonic dystrophy type 1 (cDM) is caused by the large-scale expansion of a (CTG•CAG)n repeat in DMPK and DM1-AS." (PMID 31766224, 2019). "Myotonic dystrophy type 1 (DM1) is a severe neuromuscular disorder caused by the expression of trinucleotide repeat-containing DMPK transcripts." (PMID 31116797, 2019). "Myotonic dystrophy type 1 is a multisystem disorder caused by the expansion of a trinucleotide repeat in the DMPK gene." (PMID 31164682, 2019). "The most nominally significant single SNP is rs527221 located in the DMPK gene, which is responsible for causing type 1 myotonic dystrophy." (PMID 30008175, 2018). "Myotonic dystrophy type 1 (DM1) is a neuromuscular disease caused by expanded CUG repeats in the 3′-untranslated region of the DM protein kinase (DMPK) transcript." (PMID 28379182, 2017). "RNA-mediated gain-of-function mechanism has been shown to underlie myotonic dystrophy type 1 that is caused by expansion of the CTG repeat in the 3’UTR of the DMPK (Dystrophia myotonica protein kinase) gene." (PMID 28832669, 2017). "The most common type 1 form (DM1, also called Steinert disease) is caused by the abnormal expansion of a repeated CTG trinucleotide in the 3′UTR of the DMPK gene." (PMID 28188264, 2017).
myotonic dystrophy type 1 (continued). "Myotonic dystrophy type 1 (DM1) is a neuromuscular disorder caused by an expansion of CUG repeats in the 3' UTR of the DMPK gene." (PMID 26824521, 2016). "Myotonic Dystrophy type 1 (DM1) originates from alleles of the DMPK gene with hundreds of extra CTG repeats in the 3′ untranslated region (3′ UTR)." (PMID 27805016, 2016). "Myotonic dystrophy type 1 is caused by abnormal expansion of a CTG-trinucleotide repeat in the gene encoding Dystrophia Myotonica Protein Kinase (DMPK), which in turn leads to global deregulation of gene expression in affected individuals." (PMID 25605794, 2015). "Myotonic dystrophy type 1 (DM1) is an autosomal dominant multisystemic disorder caused by expansion of CTG triplet repeats in 3′-untranslated region of DMPK gene." (PMID 25753670, 2015). "Myotonic dystrophy type 1 (DM1) is caused by an unstable expanded CTG repeat located within the DMPK gene 3’UTR." (PMID 26339785, 2015). "Myotonic Dystrophy type 1 (DM1) is a multisystemic disease caused by toxic RNA from a DMPK gene carrying an expanded (CTG•CAG)n repeat." (PMID 25799359, 2015). "Myotonic dystrophy type 1 (DM1) is an autosomal dominant neuromuscular disease caused by expansion of a CTG trinucleotide repeat in the DMPK gene." (PMID 24795756, 2014). "In fact, increases in trinucleotide repeats in DMPK are believed to be the cause of myotonic dystrophy type 1." (PMID 25010591, 2014). "Myotonic dystrophy type 1 (DM1) is caused by a CTG repeat expansion mutation in the 3′ non-coding region of the dystrophia myotonica protein kinase (DMPK) gene." (PMID 25303993, 2014). "Myotonic dystrophy type 1 is an autosomal dominant neuromuscular disorder that is caused by the expansion of a CTG trinucleotide repeat in the DMPK gene." (PMID 26317000, 2013). "Myotonic dystrophy type 1 (DM1) is caused by an unstable CTG repeat expansion in the 3′UTR of the DM protein kinase (DMPK) gene." (PMID 23209425, 2012). "Myotonic dystrophy type 1 (DM1) is caused by the expansion of CUG repeats in the 3’ UTR of DMPK transcripts." (PMID 22453899, 2012). "Myotonic dystrophy type 1 (DM1) is an autosomal dominant neuromuscular disorder caused by the abnormal expansion of CTG repeat sequences in the 3′ untranslated region (3′UTR) of the DMPK gene." (PMID 40565550, 2025). "Myotonic dystrophy type 1 (DM1) is an autosomal dominant inherited progressive multisystemic disorder caused by an unstable CTG trinucleotide repeat expansion in the non-coding region of the DM1 protein kinase (DMPK) gene on chromosome 19." (PMID 38778932, 2024). "Myotonic dystrophy type 1 (DM1) is an autosomal dominant multisystemic disease caused by a CTG expansion in the 3′ untranslated region of the myotonic dystrophy protein kinase (DMPK) gene." (PMID 38832025, 2024). "In case 5a, the pregnant woman carried an expanded DMPK allele, causing Myotonic dystrophy type 1." (PMID 37829280, 2023). "Myotonic dystrophy type 1 (DM1) is an autosomal dominant neuromuscular disease with mutlisystemic features caused by the expansion of a CTG trinucleotide found in the 3’ untranslated region (UTR) of the DMPK gene, located on chromosome 19q13.3." (PMID 37627588, 2023). "Myotonic dystrophy type 1 (DM1) is an autosomal dominant hereditary disease caused by abnormal expansion of unstable CTG repeats in the 3′ untranslated region of the myotonic dystrophy protein kinase (DMPK) gene." (PMID 36767649, 2023). "Myotonic dystrophy type 1 (DM1) is a multi-systemic trinucleotide repeat disorder resulting from an expansion of nucleotides CTG (CTGexp) in the DNA encoding DM1 protein kinase (DMPK)." (PMID 35642886, 2022). "Myotonic dystrophy type 1 (DM1) is an autosomal inherited neuromuscular disease caused by aberrant expanded (CTG) trinucleotide repeats in the 3′ untranslated region (3′UTR) of the DMPK gene." (PMID 34490258, 2021). "Myotonic dystrophy type 1 (DM1) is caused by a CTG repeat expansion in the DMPK gene." (PMID 33497365, 2021).